NUPR1 (nuclear protein 1, transcriptional regulator)
Diseases named in the same sentence as NUPR1 in open-access papers (continued):
Sharing a sentence is not in itself a finding about the gene and the disease.
tumor (continued). "NUPR1 controls the expression of genes critical to angiogenesis and tumor cell migration and invasion, facilitating the development and metastasis of metastatic breast cancer." (PMID 37854285, 2023). "Relative to the LV-sh-NC group, the tumor growth rate and tumor volume were markedly decreased in the LV-sh-NUPR1 group (p < 0.05)." (PMID 37305393, 2023). "In lung and breast cancers (LUAD, LUSC, and BRCA), repression of NUPR1, in combination with conventional anticancer therapies, has been proven to control tumor growth." (PMID 37628602, 2023). "Previous studies have shown that NUPR1 affects the biological functions of tumor cells by regulating cell apoptosis and proliferation, and angiogenesis." (PMID 37854285, 2023). "NUPR1, as a stress-induced protein, appears to be involved in a variety of stress-related functions and can promote tumor growth and aggressiveness." (PMID 37854285, 2023). "Results from the in vivo experiment also revealed that the tumor growth of BLCA can be delayed by inhibiting the expression of NUPR1." (PMID 36468653, 2023). "Although studies have reported that YAP activation is required for the development of tumor cell stemness, reports have also shown that YAP inactivation promotes stem-cell-like tumor cell growth by downregulating Nupr1 and even YAP exerts anticancer activity." (PMID 37614365, 2023). "The radioresistant role of NUPR1 was determined by colony formation assay, comet assay in vitro, and xenograft tumor models in vivo." (PMID 36258210, 2022). "NUPR1 overexpression significantly increased tumor volume and weight in the xenograft mouse model, while NUPR1 knockdown suppressed tumor growth." (PMID 36307402, 2022). "In general, NUPR1 is critical in regulating mitochondrial-related ferroptosis, either genetic or pharmacological inhibition of NUPR1 presents tumor-killing activity." (PMID 35688814, 2022). "The results supported the notion that excessive ROS generated by CYPs contributed to oxidative stress and radiation sensitivity in tumor cells with NUPR1 inactivation." (PMID 36258210, 2022). "NUPR1 is a transcriptional coregulator strongly induced by cellular stresses, and has the ability to mediate both tumor suppression and tumor development, presumably through its unique role in distinct transcriptional complexes." (PMID 33542201, 2021). "Although the precise mechanisms underlying the regulation of this process need to be investigated further, our data showed that NUPR1 is a promising druggable target against tumor resistance." (PMID 33542201, 2021). "NUPR1 participates in the regulation of tumor cell autophagy, apoptosis, growth, migration, and invasion; however, no study describing the association with NRP1 has been reported before." (PMID 34249735, 2021). "Translocation of cytoplasmic YAP into the nucleus can upregulate the expression of the Nupr1, a tumor suppressor." (PMID 31450647, 2019). "The current study was designed to better understand the mechanisms by which targeting NUPR1 results in its tumor growth-inhibiting effects." (PMID 30451898, 2018). "NUPR1 is a transcription factor that has been reported to show tumor inhibiting and promoting activities." (PMID 30042885, 2018). "A recent study reported NUPR1 acted as a negative regulator of tumor repopulating cells (TRCs) growth." (PMID 30042885, 2018). "We found that NUPR1 knockdown decreased cell viability and colony formation and increased tumor cell sensitivity to sorafenib treatment." (PMID 27336713, 2016). "In 9 of the 17 (53%) patients analyzed, NUPR1 mRNA expression was higher in the tumor samples than in NL tissues." (PMID 27336713, 2016). "Among them BNIP3 (down-regulated in HD-MM), a downstream target of NUPR1, is a novel hypoxia-inducible pro-apoptotic mitochondrial member of the Bcl-2 family which acts as tumor-suppressor by regulating apoptosis in normal and malignant cells." (PMID 26056083, 2015).
tumor (continued). "Consequently, tumor size and NUPR1 promoter methylation were found to be independent predictors of GBM patients’ overall survival (OS)." (PMID 41596413, 2026). "The overarching rationale was to create a multi-faceted epigenetic panel that captures different aspects of GBM biology: DNA repair and chemoresistance (MGMT), stress response and oncogenic signaling (NUPR1), tumor suppression (NDRG2), and developmental pathway activation (GLI1)." (PMID 41596413, 2026). "A recent study has suggested that inhibiting NUPR1 activity could sensitize tumor cells to chemotherapeutic agents, thereby improving treatment efficacy." (PMID 41596413, 2026). "Notably, NUPR1 expression was higher in the tumor regions compared to non‐tumor areas, indicating its predominant expression in TAMs." (PMID 40305758, 2025). "In addition, Nupr1 has been found to play an important role in the expression of TRB3 under CHOP-induced RES in human tumor cells." (PMID 38771421, 2025). "However, these researches predominantly focused on the direct impact of NUPR1 within tumor cells, neglecting a comprehensive exploration of its roles within the TME." (PMID 40305758, 2025). "Interestingly, Zbp1−/− tumor cells showed lower expression of H2afz, Nme1, Ran, and Ybx1, but higher expression of Nupr1 compared to WT cells." (PMID 41430036, 2025). "Compared with the tumor adjacent, NUPR1 expression was higher in TNBC." (PMID 41429768, 2025). "Based on the metabolic analysis, the NUPR1-Mac-C2 cluster exhibited high metabolic activity because of high expression of genes involved the TCA cycle and other pro-tumorigenic pathways, thereby suggesting a close association with tumor growth." (PMID 40145099, 2025). "All in all, our study suggests that suppression of the tumor Gln metabolism or inhibition of the NUPR1-mediated adaptive stress response in combination with RT could be a promising clinical strategy for the irradiation of tumor cells." (PMID 40707944, 2025). "Furthermore, in vivo assays utilizing two murine HCC models demonstrated that pharmacological inhibition of NUPR1 significantly suppressed tumor growth, accompanied by increased M1 macrophage polarization and enhanced CD8+ T cell activity." (PMID 40305758, 2025). "In tumor environments, NUPR1 likely suppresses ferroptosis to support cell survival, whereas in OA—characterized by chronic inflammation and oxidative stress—it may facilitate ferroptosis and cartilage degradation." (PMID 40782567, 2025). "The findings revealed a significantly higher abundance of NUPR1+macrophages in tumor tissues." (PMID 40305758, 2025). "Pharmacological targeting of NUPR1 reverses M2 polarization, curtails tumor growth, and augments the efficacy of PD‐1 blockade in preclinical models, positioning NUPR1 as both a potential biomarker for immunotherapy responsiveness and a therapeutic target to boost immunotherapy efficacy in HCC." (PMID 40305758, 2025). "Additionally, tumor‐derived lactate is shown to upregulate NUPR1 expression in macrophages via histone lactylation, perpetuating a feedback loop that intensifies immune suppression." (PMID 40305758, 2025). "Additionally, beyond tumor cells, stromal cells such as fibroblasts also contribute to the acidic microenvironment, potentially influencing NUPR1 regulation in macrophages." (PMID 40305758, 2025). "However, in contrast to L-DOXR cells, mRNA level of NUPR1 was barely detectable in the WT cells and WT cell-derived tumor tissues." (PMID 38536720, 2024). "Silencing NUPR1 led to slower tumor body and decreased tumor volume." (PMID 37305393, 2023). "Malignant epithelial cells showed elevated NUPR1 expression, which may have boosted tumor aggressiveness." (PMID 36698183, 2023). "NUPR1 is not only an inducer of cell and tumor growth, but also an inhibitor of tumor growth." (PMID 36468653, 2023). "Moreover, in vivo experiment revealed that the tumor growth of BLCA can be delayed by inhibiting the expression of NUPR1." (PMID 36468653, 2023).
tumor (continued). "Finally, we confirmed the upregulation of Nupr1 in tumours by RT-qPCR, a stress-induced protein involved in sorafenib resistance and NFκB and ERK pathway crosstalk." (PMID 37946160, 2023). "NUPR1-overexpressing MHCC-97H cells enhanced tumor growth in nude mice." (PMID 36258210, 2022). "NUPR1 is an intrinsically disordered protein of 8 kDa molecular weight, also called P8, which is lowly expressed under physiological conditions and is transcriptionally activated by stress and the tumor microenvironment." (PMID 36275899, 2022). "Importantly, we also found that NUPR1 KD resulted in an obvious reduction in the volume and weight of tumours formed by Cal27 cells inoculated in the subcutis of nude mice." (PMID 35462576, 2022). "Overexpression of FTL, GPX4 and NUPR1 in UCA1+ EPCAM+ cells suggests these key genes may be upregulated further along the RMC oncogenic program to increase protection of the tumor against cell death induced by ferroptosis." (PMID 35837094, 2022). "Increasing evidence indicated that NUPR1 could be activated by intracellular ROS and empower tumor cells to survive upon oxidative stress." (PMID 36258210, 2022). "Furthermore, overexpression of NUPR1 in tumor cells significantly increased the distribution of AhR to lysosome marker LAMP1." (PMID 36258210, 2022). "NUPR1 overexpression in xenograft tumor samples was further demonstrated by IHC." (PMID 36307402, 2022). "Thus, downregulating NUPR1 decreases tumor size, abrogating the effect of Tam resistance on tumor growth due to the activation of premature senescence." (PMID 33542201, 2021). "Consistent with our in vitro observations, NUPR1-knockdown (NUPR1KD) or LCN2-knockdown (LCN21KD) PANC1 cells were more sensitive to IKE-induced tumor suppression compared to control groups in vivo, in a model in which immunodeficient mice were bearing human PDAC cells." (PMID 33510144, 2021). "Moreover, immunohistochemical staining revealed that Ki-67 expression was remarkably decreased in NUPR1-depleted xenografts, indicating that the knockdown of NUPR1 attenuated tumor proliferation." (PMID 34030133, 2021). "Interestingly, recent studies have shown that Nupr1 plays an important role in CHOP-induced expression of TRB3 in response to ER stress in human tumor cells and neuronal cells." (PMID 30674641, 2019). "It was already described that genetic inhibition of NUPR1 induces tumor growth arrest." (PMID 30451898, 2018). "Furthermore, both our in vitro and in vivo data confirmed that NUPR1 has a critical role in the regulation of tumor cell growth, tumor migration and invasive capacity and survival of HCC cells, suggesting its oncogenic role in HCC." (PMID 27336713, 2016). "Furthermore, analysis of tumor cells in the GSE149614 dataset revealed that “don't eat me” ligands CD47, CD24, human leukocyte antigen A (HLA‐A), and HLA‐B were significantly upregulated in tumor cells from NUPR1‐high samples, indicating a potential effect of NUPR1+ macrophages on tumor cells." (PMID 40305758, 2025). "Additionally, we observed that when macrophages were co‐cultured with TCM derived from tumor cells supplemented with lactate, or treated with Rotenone, which promotes glycolysis, there was a notable upregulation of NUPR1 expression and histone lactylation modifications in THP1 cells." (PMID 40305758, 2025). "Furthermore, bioinformatics analyses using publicly available gene expression datasets revealed upregulation of both FTH1 and NUPR1 mRNA expression in HCC tumor groups compared to normal groups, with a significant positive correlation between NUPR1 and FTH1 mRNA expressions in these HCC datasets." (PMID 38802795, 2024). "Additionally, the expression of NUPR1 increased with tumor aggressiveness." (PMID 36698183, 2023).
tumor (continued). "The covariates included in the model were the promoter methylation levels of the NUPR1, NDRG2, and GLI1 genes, as well as age and tumor size." (PMID 41596413, 2026). "This research unveils a novel role for NUPR1 in augmenting the efficacy of ICB therapy in HCC, providing insights into the molecular mechanisms of tumor immune evasion and outlining new strategies for targeting TAMs to boost T‐cell antitumor responses." (PMID 40305758, 2025). "NUPR1 inhibits ERK and JNK signaling to establish an immunosuppressive environment conducive to tumor progression in HCC." (PMID 41417432, 2025). "Subsequently, we measured the lactate content in tumor tissues and analyzed the expression levels of CD206 and NUPR1." (PMID 40305758, 2025). "The TMA1 cohort of Zhongshan Hospital was used for mIF staining to examine the expression of NUPR1 and CD68 in tumor tissues compared to adjacent tissues." (PMID 40305758, 2025). "Mechanistically, NUPR1 inhibits the ERK and JNK signaling pathways, thereby creating an immunosuppressive milieu conducive to tumor progression." (PMID 40305758, 2025). "(I) Representative images show the expression of NUPR1 and HDAC11 on a TNBC TMA with different tumor grades (grades 1, 2, and 3)." (PMID 38536720, 2024). "In the LIHC dataset, we found a comparable group of normal-adjacent samples, which demonstrated the upregulation of EEF1A2, NUPR1, and MAPT proteins in the tumor group." (PMID 37628602, 2023). "Overall, these findings suggest that NUPR1 can promote the proliferation of HCC cells and tumor growth in vitro and in vivo." (PMID 36307402, 2022). "In prostatic cancer (PC), TAGLN (tumor suppressor) and HLA had higher expression in the periphery, whereas NUPR1 and KLK4 etc. were expressed higher in the tumor core." (PMID 36313703, 2022). "The contrasting methylation patterns of MGMT/NUPR1 and NDRG2/GLI1 in GBM may shed light on their opposing roles in tumor development and progression." (PMID 41596413, 2026). "Additionally, we discovered that lactate from tumor cells induces histone H3K18 lactylation in macrophages, which upregulates NUPR1 transcription." (PMID 40305758, 2025). "However, we also noted an increase in the expression of certain tumor related genes, including SAA1, KRT19 and NUPR1." (PMID 38951896, 2024). "To further substantiate the clinical relevance of our findings, we analyzed the NUPR1 expression in tissues from LIHC patients, which showed that the expression of NUPR1 was significantly increased in tumor tissues compared to normal tissues." (PMID 36307402, 2022). "Meanwhile, in the transwell migration assay, NUPR1 overexpressing tumor cells (MHCC-97HLV-NUPR1, 57.00 ± 4.359, and SK-Hep1LV-NUPR1, 153.3 ± 7.126) exhibited a significantly more invasive phenotype than control cells (MHCC-97HLV-NC, 29.33 ± 2.186, and SK-Hep1LV-NC, 85.00 ± 1.528) (p < 0.01)." (PMID 36307402, 2022). "Additionally, NUPR1 KD efficiently suppressed TFE3 and “TFE3-responsive genes” expression in the xenograft tumour models." (PMID 35462576, 2022). "LCN2 (but not NUPR1) mRNA expression was upregulated in the PDAC tumor group compared to the normal group." (PMID 33510144, 2021). "Interestingly, Nupr1 is known to regulate both CHOP and TRB3 in human tumor cells and neuronal cells." (PMID 30674641, 2019). "Immunohistochemical analysis showed high NUPR1 expression in all the HCC patients studied; moreover, NUPR1 displayed a nuclear localization in the tumor hepatocytes but not in NL hepatocytes." (PMID 27336713, 2016). "L-DOXR cells and L-DOXR cell-derived tumor tissues showed high-level expression of NUPR1, which was consistent with the poor clinical outcomes, including low overall survival (OS) and disease-free survival (DFS), in chemotherapy-treated TNBC patients with high NUPR1." (PMID 38536720, 2024).
tumor (continued). "Opportunities to trial TFP for GBM may be at the onset of recurrent disease, where average NUPR1 expression is higher, or alternatively perioperatively in newly diagnosed patients with GBM, when residual tumor cells at the margin of the resection cavity are acutely reexposed to CSF." (PMID 37878712, 2023). "In our study, high-sensitivity label-free quantitative proteomics analysis revealed nuclear protein 1 (NUPR1) as the most significantly upregulated protein in formalin-fixed paraffin-embedded tumour samples derived from OSCC patients with or without lymphatic metastasis." (PMID 35462576, 2022). "Additionally, NUPR1 depletion in these TamR cells rather than the parental cells significantly decreased tumor volume, and the number of tumors formed in the mammary fat pad in an athymic nude mouse model with Tam treatment." (PMID 33542201, 2021). "While expression of Dddit4, FGF21, and Nupr1 was decreased in tumor compared to non-tumor tissue." (PMID 32363190, 2020). "When mouse embryo fibroblasts (MEFs) from wild-type and Nupr1-null mice were transformed with rasV12 mutant and E1A oncogene, Nupr1-/- MEFs could not form colonies in soft agar and no tumor was observed with transformed Nupr1-/- MEFs following subcutaneaous or intraperitoneal injections." (PMID 27285315, 2016). "Using patient-derived tumor and adjacent non-cancerous tissues, we found that expression of the SLC1A5, SLC7A5, and SLC38A1, and NUPR1 is a rescue mechanism induced by GLS inhibition." (PMID 40707944, 2025).
infection (9 papers, 2016 to 2024). The state of being infected such as from the introduction of a foreign agent such as serum, vaccine, antigenic substance or organism. "IFNB is essential to start the cell fate pathway driven by NUPR1, a gene signature that contributes to a progressive infection in human cells." (PMID 35492305, 2022). "Infection of three different shRNA sequences against NUPR1 resulted in a strong depletion of NUPR1 expression compared to that in cells infected with the firefly luciferase control (control shRNA, con) (left)." (PMID 33542201, 2021). "NUPR1 mRNA was upregulated by a mean log10 fold change of 1.3 at 48h in MDMs post-infection compared to uninfected cells." (PMID 31344041, 2019). "NUPR1 was found to be upregulated in the host response to infection by Histoplasma capsulatum and detected as an upstream regulator in the host transcriptome associated with other fungal and bacterial infections." (PMID 31344041, 2019). "Specifically, NUPR1 gene expression was the most upregulated at the intersections of all acute infection time points." (PMID 27222466, 2016). "Given that elevated NUPR1 expression leads to deactivation of the autophagy-associated apoptosis induced by metabolic stress, our results suggest that ASFV affects multiple organs (spleen and lymph nodes) to express NUPR1 at an early stage of infection, for survival and replication." (PMID 38847223, 2024). "Next, to evaluate if M. leprae induction of NUPR1 gene expression was dependent on IFN-β signaling, we incubated MDMs with αIFNAR antibody prior to infection and, in six donors, observed a drastic decrease in NUPR1 expression at 24 and 48h." (PMID 31344041, 2019). "Upregulation of the expression of the NUPR1 gene was also observed in mouse brains infected with JEV or WNV, suggesting that TBFVs and encephalitogenic MBFVs share this ability to induce metabolic stress during infection." (PMID 27222466, 2016).
intestinal diseases (1 paper, 2024). "Moreover, further research on the role of Nupr1 in intestinal diseases could offer more possibilities for developing targeted treatment strategies." (PMID 39508252, 2024).